RALA (RAS like proto-oncogene A)
Diseases named in the same sentence as RALA in open-access papers (continued):
Sharing a sentence is not in itself a finding about the gene and the disease.
cancer (continued). "The variety and occasional discordance in the apparent roles of RALA and RALB both within and between cancer types suggest that diverse roles are commonly assumed by the two RALs in cancer." (PMID 39272901, 2024). "In this context, inhibition of RalA would impair EVs trafficking and release, potentially impacting on vesicular FAM3C-mediated carcinoma cell invasiveness." (PMID 36632230, 2023). "Here we review the structure, regulatory mechanisms and post-translational modifications of RALA and RALB to gain insight into the structural basis for their conserved and contradictory functions in cancer." (PMID 35626682, 2022). "In this review we highlight the overlapping and divergent roles of RALA and RALB in cancer, describe their effectors, examine their potential as therapeutic targets, and provide important considerations for future RAL-GTPase research." (PMID 35626682, 2022). "Similarly, our study also predicts target genes like E2F1, WNT1, RALA, and PTEN that reveal their involvement in cancer progression." (PMID 38741808, 2024). "Hence, a preliminary investigation of the iTAAs in cancer patients revealed an increase in autologous antibodies of TAA: HCC1, RalA, zeta, and p1617." (PMID 37336938, 2023). "PPP2R1B also specifically contributes to regulation of a signaling pathway downstream of RAS, by decreasing RalA phosphorylation and activity: thus, decreased PPP2R1B expression may contribute to increased cancer cell migration and EMT-high state." (PMID 37170215, 2023). "RALA and RALB can have redundant, unique, or even antagonistic functions depending on cancer type." (PMID 35626682, 2022). "This work highlights the sometimes paradoxical roles of RALA and RALB in cancer." (PMID 35626682, 2022). "While GLUT4 is associated with metastasis of head and neck squamous cell carcinoma and is involved in EMT, a specific role for RALA-mediated GLUT4 trafficking in cancer has not yet been established." (PMID 35626682, 2022). "Previous studies showed that RALA and RALB might play distinctive oncogenic roles in human cancers, as RALB contributed to the survival of human cancer cells." (PMID 35409173, 2022). "However, despite decades of study, the functions of RALA and RALB in normal cell and cancer biology remain incompletely understood." (PMID 35626682, 2022). "Meanwhile, multiple studies reported that Ras-driven transformation depends on RalA and not RalB in various human cancer cell lines." (PMID 31201267, 2019). "Very interestingly, RalB (but not RalA) protein expression increased in a manner consistent with disease progression (normal < in situ < invasive < metastatic tissues), supporting once more a crucial role for RalB in cancer invasion and metastasis." (PMID 30320548, 2018). "Indeed, RalA and RalB have antagonistic effects on cancer cell migration and RalA but not RalB drives delivery of membrane proteins to the basolateral surface of epithelial cells." (PMID 19890390, 2009). "In addition, a better understanding of the full spectra of post-translational modifications of RALA and RALB and how these modifications alter subcellular localization and effector utilization is required to provide a framework for their various roles in cancer." (PMID 35626682, 2022). "Given the frequently non-redundant roles of RALA and RALB in cancer, the development of paralog-specific inhibitors would provide the field with invaluable research tools and potentially powerful therapeutics." (PMID 35626682, 2022).
infection (3 papers, 2015 to 2021). The state of being infected such as from the introduction of a foreign agent such as serum, vaccine, antigenic substance or organism. "Additionally, levels of genes associated with the EGFR/MAPK pathway, such as argos (aos), rhomboid (rho), Sox21a, and string (stg), appeared increased following Ecc15 infection in control midguts in a RalA-dependent manner." (PMID 34096503, 2021). "The 3, 6 and 24 h post-infection samples were stained using the antibody to the M. hyorhinis P70 protein and to the early endosome marker RAB5, the late endosome marker RAB7, the exocytosis marker RALA and the autophagosome marker LC3." (PMID 26544880, 2015).
cardiac disease (1 paper, 2013). "Future studies will examine the contribution of RalA-dependent and RalA-independent signaling pathways in Rgl2-induced activation of the PI3K/Akt signaling cascade, and whether Rgl2 represents a novel therapeutic target in cardiac disease." (PMID 24069211, 2013).
neurodevelopmental disorder (1 paper, 2025). A behavioral and cognitive disorder with onset during the developmental period that involves impaired or aberrant development of intellectual, motor, or social functions. "Further investigations aiming at unravelling the functional impact of disease‐causing RALA variants will offer important insights into the molecular pathways underlying human neurodevelopmental disorders." (PMID 39918382, 2025).
RALA also shares sentences with these, for which no sentence is quoted: Glucose intolerance (2 papers); Hepatic steatosis (2); Hyperinsulinemia (2); onchocerciasis (2); triple-negative breast carcinoma (2); adult T-cell lymphoma leukemia (1); Alzheimer disease (1); amyotrophic lateral sclerosis (1); Burkitt lymphoma (1); cervical squamous cell carcinoma (1); cholangiocarcinoma (1); Chronic Lymphocytic Leukemia (1); colorectal adenocarcinoma (1); COVID-19 (1); desmoplastic/nodular medulloblastoma (1); endocervical adenocarcinoma (1); esophageal cancer (1); essential thrombocythemia (1); follicular lymphoma (1); Follicular Thyroid Cancer (1); genetic disorder (1); glioblastoma (1); glioma (1); Hiatt-Neu-Cooper neurodevelopmental syndrome (1); Huntington disease (1); liposarcoma (1); lung adenocarcinoma (1); lymph node metastasis (1); malignant peripheral nerve sheath tumor (1); metastasis (1).
A further 9 diseases each share a sentence with RALA in 1 paper.